ODF4 (outer dense fiber of sperm tails 4)
Description:
Component of the outer dense fibers (ODF) of spermatozoa which could be involved in sperm tail structure, sperm movement and general organization of cellular cytoskeleton.
Synonyms: OPPO1; CT136; CT134
Tractability: Antibody: UniProt predicts a signal peptide or a membrane-spanning region.
Gene: Protein-coding gene on chromosome 17 (8,339,840 to 8,346,048, forward strand). Ensembl gene ENSG00000184650.
Subcellular location: Membrane
Subcellular location (Human Protein Atlas): Principal piece
Gene Ontology:
Molecular function: protein binding
Cellular component: membrane
Genetic constraint (gnomAD): Loss-of-function variants: 10 observed, 15.08 expected, observed/expected ratio (o/e) 0.66, 90% interval 0.41 to 1.12. The upper end of that interval is the gene's LOEUF score, 1.12, which puts it in group 4 of 6, group 1 being the genes least tolerant of losing a copy. Missense variants: 278 observed, 315.3 expected, observed/expected ratio (o/e) 0.88, 90% interval 0.8 to 0.97. Synonymous variants: 125 observed, 125.65 expected, observed/expected ratio (o/e) 0.99, 90% interval 0.86 to 1.15.
Homologues: Orthologues: chimpanzee ODF4 (98% identical), macaque ODF4 (49% identical), dog ODF4 (25% identical).
Diseases named in the same sentence as ODF4 in open-access papers:
ODF4 is named in the same sentence as 13 diseases in open-access papers, as found by Europe PMC text mining. Sharing a sentence is not in itself a finding about the gene and the disease. The quoted sentences say what the papers report.
breast carcinoma (3 papers, 2015 to 2022). "ODF4 (outer dense fiber of sperm tails 4) has been reported to have a high expression in breast cancer, prostate cancer, basal cell carcinoma and chronic myeloid lymphoma." (PMID 31141819, 2019). "In another study, ODF4 was significantly highly expressed in breast cancer tissue and could be used in combination with other biomarkers to differentiate between cancer and normal tissues." (PMID 36339718, 2022). "Expression of ODF4 and RH-OXF2 was detected in 62.5% and 60% of breast cancer tissues but in 22.5 and 17.5% ofnormal tissues examined respectively." (PMID 26464818, 2015). "ODF4 and RHOXF2 expressions were detectedin 62.5 and 60% of breast cancer tissues but alsoin 22.5 and 17.5% of normal tissues examinedrespectively." (PMID 26464818, 2015). "ODF4 and RHOXF2 are proposed as putative breast cancer biomarkersat the transcript level." (PMID 26464818, 2015).
male infertility (3 papers, 2020 to 2025). The inability of the male to effect fertilization of an ovum after a specified period of unprotected intercourse. "This study is supported by the rescue experiment; the abnormalities and male infertility caused by Odf4 deletion were reversed by Odf4 restoration." (PMID 36804949, 2023). "Knockout of ODF4 in male mice results in curved and abnormally motile sperm tails, leading to male infertility." (PMID 40584277, 2025).
asthenozoospermia (1 paper, 2018). "It is indispensable to produce Odf3 and Odf4 KO mice to decipher their roles in the construction of ODFs and axonemes and in the pathogenesis of asthenozoospermia." (PMID 29168316, 2018).
Fibroadenoma (1 paper, 2015). A benign tumor of the breast characterized by the presence of stromal and epithelial elements. "ACRBP, ODF4 and RHOXF2 were expressedin 60, 10 and 10% of fibroadenomas respectively.None of the fibroadenoma samples showed SPATA19expression." (PMID 26464818, 2015).
infertile (1 paper, 2023). "Odf4−/− males were healthy and normal vaginal plugs formed when they mated with females; however, they were almost completely infertile, which resulted in a severely reduced average number of pups." (PMID 36804949, 2023).
transitional cell carcinoma (1 paper, 2018). A malignant neoplasm arising from the transitional epithelium, usually affecting the urinary bladder, ureter, or renal pelvis. "This study aimed to evaluate the diagnostic value of outer dense fiber 4 (ODF4), melanoma-associated antigen A3 (MAGEA3), and MAGEAB4 mRNAs in transitional cell carcinoma (TCC), using a small amount of cell reverse transcriptase-polymerase chain reaction (RT-PCR) on urinary exfoliated cells." (PMID 28865418, 2018).
tumor (3 papers, 2018 to 2022). "Afsharpad determined ODF4 expression in urinary exfoliated cells, cancerous tissue and tumor-free tissue to confirm its diagnostic and surveillance potential." (PMID 31141819, 2019). "In this study, qRT-PCR showed that the expression levels of two genes, DCLRE1C and ODF4, differed significantly between normal and tumor tissues." (PMID 36339718, 2022). "The frequent expression of ODF4 within TCC tumor tissues and its correlation with the expression data from urine correctly negates that the expression pattern of ODF4 at mRNA level was in response to the BPH, but not to the TCC status (unpublished data)." (PMID 28865418, 2018). "Among all studied candidate genes, only ODF4, melanoma-associated antigen (MAGE) A3, and MAGEB4 mRNA were detectable in more than 50% of both TCC tissues and urinary exfoliated cells and in less than 20% of tumor-free matched, adjusted bladder tissues." (PMID 28865418, 2018). "In addition, ODF4 was expressed at a lower level in the tumor group than in the DCLRE1C group." (PMID 36339718, 2022).
ODF4 also shares sentences with these, for which no sentence is quoted: cancer (4 papers); basal cell carcinoma (1); chronic myeloid leukaemia (1); ductal carcinoma (1); neurological disease (1); prostate carcinoma (1).